RN7SL351P (RNA, 7SL, cytoplasmic 351, pseudogene)
Gene: Miscellaneous RNA gene on chromosome 11 (126,245,035 to 126,245,282, forward strand). Ensembl gene ENSG00000240098.
Homologues: Orthologues: chimpanzee Metazoa_SRP (98% identical), dog Metazoa_SRP (67% identical). Paralogues in human: RN7SL1 (79% identical), RN7SL493P (79% identical), RN7SL2 (79% identical), RN7SL3 (79% identical), RN7SL177P (78% identical), RN7SL660P (78% identical), RN7SL301P (78% identical), RN7SL126P (77% identical), RN7SL336P (77% identical), RN7SL11P (77% identical), RN7SL220P (77% identical), RN7SL664P (77% identical), and 699 more.